IL6 (interleukin 6)
Diseases named in the same sentence as IL6 in open-access papers (continued):
Sharing a sentence is not in itself a finding about the gene and the disease.
cancer (continued). "Even in the early stages of cancer progression, tumors produce various factors including cytokines, chemokines, growth factors, and transcription factors; this includes IL-6, CRP, and tumor necrosis factor (TNF)-α, to name a few." (PMID 30042700, 2018). "Given the critical role of IL-6 in altering the balance between Treg and Th17 cells, controlling IL-6 activities is potentially an effective approach in the treatment of various types of cancer." (PMID 29853890, 2018). "Administration of TCZ interferes with the IL-6-mediated pathways that enhance the survival properties of all cancer cells and the self-renewal properties of CSCs." (PMID 29351275, 2018). "Our results also support previous data on the prognostic significance of high plasma levels of IL-8 and IL-6 in cancer patients, rendering a combination of these markers appealing in the quest for robust and specific prognostic markers in a cancer setting." (PMID 29324871, 2018). "IL-1β was shown to increase cancer sphere formation and stem cell marker expressions in colon cancer, while IL-6, IL-8, CCL2 and transforming growth factor-β promoted breast cancer stemness." (PMID 30486830, 2018). "Shortly after cancer treatment, higher levels of sTNF-RII were associated with increased memory complaints, and on average 5 years after cancer treatment, elevated IL-6 and TNFα levels were associated with worse verbal memory." (PMID 30442190, 2018). "Many patients with GI cancer have elevated IL-6 levels, but only a few studies have taken into consideration that IL-6 is increased in serum or plasma in patients with other types of cancer and other diseases characterized by inflammation." (PMID 30038723, 2018). "Based on these results we examined a separate cohort of A-T subjects who had baseline serum IL6 and IL8 measured previously to determine if an association existed between higher serum IL6 and IL8 levels and subsequent development of malignancy and/or death." (PMID 30586396, 2018). "Although IL-6-mediated activation of the signal transduction and activator of transcription 3 (STAT3) axis is involved in inflammation and cancer, the role of STAT3 in Helicobacter-associated gastric inflammation and carcinogenesis is unclear." (PMID 29849601, 2018). "Activated CAFs further promote cancer progression by secreting pro-inflammatory cytokines, including IL-6 and IL-8." (PMID 29335551, 2018). "IL6 is a proinflammatory cytokine with a typical protumorigenic effect, and serum levels are elevated in cancer patients." (PMID 29535825, 2018). "Interleukin-6 (IL-6) is known to stimulate STAT3 phosphorylation on tyrosine Tyr705 in many cancer cells." (PMID 30577812, 2018). "A significant increase in migration and invasion of cancer cells was also noted what indicates that IL-6 facilitates metastasis and invasion by promoting EMT48." (PMID 30310111, 2018). "Although the significance of IL-6 as a conceptual target for cancer treatment is well-documented, we still do not fully understand how anti-IL6 therapies work in vivo." (PMID 29351275, 2018). "Several studies have shown IL-6 to be a prognostic indicator of survival as well as predictive in response to therapy in many types of cancer." (PMID 30038723, 2018). "Conversely, IL-6 is regarded as an activator of cancer cells, including the enhancement of invasion activity and cell death resistance." (PMID 30042824, 2018). "The expression of IL-6 has been found to increase dramatically in cases of a number of different cancer types, including liver, colon, and ovarian cancer." (PMID 29693005, 2018). "Consistently, exosomes derived from high-metastatic cancer cells also promoted the secretion of IL-6 and IL-8 in fibroblasts." (PMID 29335551, 2018). "The pleotropic cytokine, IL-6 is highly expressed in adipose tissue and play a multifactorial role in cancer, influencing EMT, metastasis, angiogenesis, cachexia, stemness and therapeutic resistance." (PMID 29891854, 2018).
cancer (continued). "IL-6 regulates cancer stem cell, mesenchymal stem cell formation, epithelial to mesenchymal transition in cancer and is a contributing factor for chemoresistance." (PMID 29728589, 2018). "Interleukin-6 (IL-6), which can be produced by malignant tumors, is able to stimulate platelet production." (PMID 29719631, 2018). "These CAFs were enriched following neoadjuvant chemotherapy, and were shown to promote cancer stem cell self-renewal through the secretion of IL-6 and IL-8." (PMID 30380628, 2018). "Exosomal gp130, which is highly enriched in cancer exosomes, triggers the secretion of IL-6 from BMDMs." (PMID 29867925, 2018). "Inflammatory cytokines released by various cancer entities, like IL-3, IL-6, and IL-10, are capable of stimulating megakaryocytes proliferation, which can produce platelets." (PMID 30643825, 2018). "In conjunction with IL-6, IFNγ plays a major role in modulation of the cancer immune network to inhibit or promote tumor progression." (PMID 30666202, 2018). "As activated DNA damage response and genomic instability induced by exogenous stimulation was the primary reason for genomic alterations in cancer, we detected the effects of IL-6 on DNA damage and genomic instability." (PMID 30482241, 2018). "As expected, plasma levels of IL-8, IL-6, TNFα, IL-1β, and G-CSF were all significantly higher in cancer patients compared to healthy individuals." (PMID 29324871, 2018). "It is thus proposed that during PTX elimination of cancer cells, it activates inflammatory mediators, in particular IL-6, IL-8 and XIAP from cancer cells, and these cytokines can then aggravate anti-apoptosis via the TLR4 signaling pathway." (PMID 29486738, 2018). "On the other hand, certain cancers, including many bone-metastases, have an opposing phenotype and demonstrate a sustained and even enhanced proliferation due to IL-6 and similar cytokines." (PMID 30671025, 2018). "Perhaps of greatest clinical relevance, activation of STAT3 through IL-6 signaling allows cancer cells to escape immune surveillance and can prevent clearance of senescent cells by the immune system." (PMID 29868482, 2018). "In vivo and in vitro experimental studies showed an impact on osteoclast formation and upregulation of TNF-α and Interleukin-6 (IL)-6 generation, epithelial-to-mesenchymal transition, be it in a cancer model and a neurotoxic effect." (PMID 29316724, 2018). "IL-6 in general, and IL-6 transsignaling (signaling mediated by the soluble IL-6R) in particular, are known to play deleterious roles in cancer." (PMID 29441069, 2018). "IL-6 acts as a growth factor and fuels cancer progression through activating a series of downstream signalling cascade including gp130, JAK/STAT, MAPK, and Akt." (PMID 29695771, 2018). "To confirm the role of inflammatory signals in M1-induced EMT, we neutralized IL-6, IL-1β, and TNFα in M1-treated A549 cancer cells and examined the expression of EMT markers." (PMID 30218063, 2018). "Inflammation in particular has been shown to be key in promoting cancer proliferation and differentiation, with IL-6 being an integral player." (PMID 30671025, 2018). "It is clear that IL-6 plays a critical role in the pathobiology of cancer, due in part to its impact on cancer stem cells." (PMID 29351275, 2018). "The proposed therapeutic mechanism of CPS and CRC on cancer cells was reported to inhibit the activation of NF-κB and block the activation of signal transducer and activator of transcription 3 (induced by IL-6)." (PMID 29699594, 2018). "The dysregulation of TJs leads to altered barrier function resulting in changes in levels of inflammatory cytokines such as IFN-α, IFN-gamma, IL-6 and IL-1β as seen in inflammation associated diseases such as IBD, multiple sclerosis and cancer." (PMID 30728783, 2018). "The dedifferentiation of cancer cell was inhibited through inhibition of IL-6, CCAAT/enhancer binding protein alpha (CEBPα), Spi-1 proto-oncogene (PU.1), c-Myc and E2F transcription factor 1 (E2F1)." (PMID 30373594, 2018).
cancer (continued). "From a molecular cancer point of view, thrombocytosis has been illustrated to be stimulated by cancer-mediated production of cytokines, most commonly interleukins (IL-1, IL-3, IL-6, and IL-9) and granulocyte-macrophage colony-stimulating factor (GM-CSF)." (PMID 29736362, 2018). "While studying the role of USP24 upregulation in M2 macrophages, we found that USP24 expression in M2 macrophages enhanced cancer metastasis by inducing IL-6 expression." (PMID 30266897, 2018). "An elevated level of IL-6 is related to cancer cell proliferation, angiogenesis, and metastasis via stimulation of MAPK, STAT3, and AKT signaling pathways." (PMID 29770167, 2018). "Since PN is a JAK2 covalent inhibitor and can inhibit the IL-6-induced STAT3 activation, we next examined the effect of PN on the IL-6-induced cancer cell migration." (PMID 29921758, 2018). "Keap-1 knocked-down amplified M2-macrophages induction by cancer cells, appearing as decreased IL-1b and IL-6 expression, and increased CD163 and Arg1 expression." (PMID 30180849, 2018). "The authors show that IL-6 remains a promising therapeutic strategy for diminishing cachexia in many types of cancers." (PMID 30426026, 2018). "Our results indicate that cancer cell lines significantly upregulated genes associated with M1 monocytes including PDL1, TNF-α, IL-1β, IL-6, IL-8, CCL3, and prostaglandin-endoperoxidase synthase 2 (PTGS2)." (PMID 29668679, 2018). "The cytokines, interleukin 6, and tumor necrosis factor α are known to induce neutrophilia and are involved in acute inflammatory processes and in the pathogenesis of cancer-related inflammation." (PMID 30470260, 2018). "With the increasing level of IL-6 produced by adipocytes, IL-6R was upregulated in EpCAMþ/CD133þ cancer stem cells." (PMID 30013512, 2018). "Among the growth factors secreted by adipocytes, transforming growth factor-beta (TGF-β) and interleukin-6 (IL-6) have been independently proven to be potent regulators of EMT in various cancer cells." (PMID 29891854, 2018). "Particularly, the IL-6/JAK/STAT3 autocrine activation loop is a key driver of cancer progression and metastasis in breast cancer." (PMID 29934528, 2018). "IL-6 is a pleiotropic, pro-inflammatory cytokine involved in many biological processes, including cancer and autoimmune diseases." (PMID 30038723, 2018). "IL-6 also contributes to the proliferation and inhibition of apoptosis of cancer cells, and thus, supports chronic inflammation and cancer development." (PMID 29854832, 2018). "C-reactive protein (CRP) is a prototype acute phase protein that was demonstrated to be produced in hepatocytes and regulated by growth factors in the malignant tumors such as IL-6." (PMID 29890986, 2018). "IL-6 marks sites of hypoxia in tumors, and its induction in early lesions is necessary for unrestricted cancer cell outgrowth." (PMID 29930325, 2018). "In examining a cohort of A-T subjects in which baseline serum IL8 and IL6 levels were measured previously, an association was found between higher serum IL8 levels and higher likelihood of developing malignancy and/or death in a subsequent 4–6 year period." (PMID 30586396, 2018). "In advanced cancer as well as in chronic inflammatory diseases, increase in hepatic production of hepcidin is induced by high levels of IL-6." (PMID 30294279, 2018). "These factors activate astrocytes to produce growth factors (IL-6, IL-1B, and tumor necrosis factor), resulting in a perpetuation of cancer cell growth in the neural niche." (PMID 29881714, 2018). "IL6 plasma levels have also been examined in cancer patients, and they were found to be variably but consistently elevated in cancer patients compared to healthy controls." (PMID 30072615, 2018). "Blocking IL-6 was proven beneficial towards patients with Castleman disease and inflammatory diseases, and it was well tolerated in cancer patients as well." (PMID 30064449, 2018).
cancer (continued). "It has been shown that fatty acids induce the expression and secretion of inflammatory cytokines such as IL-6, IL-8 and IL-1β via activation of NF-κB pathway in normal and cancer cells." (PMID 30510774, 2018). "Chronic inflammation, mediated by cytokines such as tumor necrosis factor alpha (TNF-α) and interleukin-6 (IL-6), has been reported to promote cancer cachexia." (PMID 29338749, 2018). "IL-6 is a key downstream target of the STAT3 signaling pathway and we observed an approximately three-fold induction in IL-6 secretion from BMDMs after cancer exosome exposure." (PMID 29867925, 2018). "Like in cancer cells, this effect was persistent through the activation of the IL-6/STAT3/NF-κB positive feedback loop, which is responsible for the persistent activation of BSFs." (PMID 29707149, 2018). "Overall, our study re-emphasizes the heterogeneous spectrum of MDSC subsets identified in cancer patients, and suggests that the IL-6/IL-8-arginase I axis is a potential therapeutic target for the ablation of MDSC-mediated immunosuppression in GC patients." (PMID 29988030, 2018). "For example the inclusion of IL-6 producing endothelial cells increases the growth rate and the proportion of cancer stem cells." (PMID 29351275, 2018). "Recently, high serum levels of IL-1β, IL-6, IL-8, and TNF-α in cancer patients have been linked to CC pathogenesis." (PMID 30513776, 2018). "Recently, several herbal medicines, including Hochuekkito (TJ-41) and Coptidis rhizoma, have been demonstrated to attenuate cancer cachexia by reducing IL-6 production, which is a critical mediator of muscle wasting." (PMID 29662645, 2018). "This was related to the maintenance of cancer stem cells since IL-6 supplementation increased mammosphere formation in ATG7 shRNA-expressing cells and was associated to dependence on autophagy for survival." (PMID 30622432, 2018). "Cancer cell studies have shown a correlation between IL-6 and chemo resistance and increased proliferation, and the use of IL-6 as a therapeutic target is currently being investigated." (PMID 30038723, 2018). "Binding of IL-6 to its receptor activates at least two signaling pathways in the IL-6 expressing cancer cells." (PMID 30013512, 2018). "This work focuses on quantifying the influence of IL-6, a pleiotropic cytokine secreted by a variety of cell types, on cancer stem cell self-renewal and survival." (PMID 29351275, 2018). "Increased IL-6 in cancer cells results in subsequent release of IL-6 by stromal cells, thus feeding into the pro-tumoural feed-forward loop and exacerbating the diseased state." (PMID 30671025, 2018). "Systemic interleukin-6 (IL-6) signaling is also crucial in inducing muscle wasting and has been shown to be involved in the pathophysiology of at least some models of cancer cachexia." (PMID 29849089, 2018). "Some studies have demonstrated a potential role of inflammation (CRP, IL-6) for general cancer pain." (PMID 30266081, 2018). "IL-6 activates proinflammatory-signaling pathways in epithelial cancers and leads to cancer progression, metastasis and therapy resistance through activation of pro-survival signals." (PMID 29423072, 2018). "Overexpression of IL-6 induces cancer cell proliferation, angiogenesis, and metastasis through stimulating STAT3, MAPK, and Akt signaling pathways." (PMID 29728589, 2018). "IL-8 and IL-6 have been shown to be expressed and released by cancer cells, and to induce NET formation in vitro." (PMID 29324871, 2018). "On the other hand, impairment of NO-dependent function in the aorta occurred only in the late phase of metastasis formation, most likely as a consequence of robust, cancer-related systemic inflammation mediated by IL-6, TNFα or other mechanisms." (PMID 29788918, 2018). "With regard to cancer cachexia, IL-6 decreased LPL activity in adipose tissue of mice and IL-1 directly modulates lipid metabolism by suppressing LPL activity." (PMID 29631586, 2018).
cancer (continued). "Previous studies have reported that pro-inflammatory cytokines, including IL-1, IL-6, TNF-α, and INF-γ, were associated with depressive symptoms in cancer patients." (PMID 30567507, 2018). "As continuous IL-6 played a different role from short-term stimulation in cancer, we first explored the effects of continuous IL-6 in HCC." (PMID 30482241, 2018). "In line with our findings, Giannoni and colleagues reported a crucial role of carcinoma-derived vesicular IL-6 in the activation of fibroblasts." (PMID 29967610, 2018). "Interleukin 6 (IL-6) and its soluble receptor sIL-6R is expressed by various human carcinoma cell lines in vitro." (PMID 30581772, 2018). "IL6 is usually secreted by activated stromal cells and is also found to be conditionally secreted by cancer cells." (PMID 28687755, 2017). "It has been confirmed that an IL-6 signalling pathway stimulates cancer progression through the IL-6 receptor on the cancer cell surface in prostate cancer." (PMID 29259311, 2017). "We also examined the relationship between ZEB1 and IL‐6 in other types of cancers using a tissue array of 448 cancer tissues from multiple organs and found other double‐positive cancers." (PMID 28618162, 2017). "Response to IL-6 in BC is closely dependent on ER and PR expression implying that hormone sensitive cancer cells are more responsive than hormone insensitive cells." (PMID 28496132, 2017). "Conditioned medium from CRISPR/Cas9-mediated IL-6 knockout primary human endothelial cells is less chemotactic for cancer stem cells in a microfluidics-based system than medium from control endothelial cells (p<0.05)." (PMID 29245982, 2017). "Serum concentrations of IL-6 and CRP are positively correlated, and recent evidence suggests that IL-6 also affects cancer cell biology." (PMID 29259311, 2017). "Especially considering the significant decrease of miR-218 in ALDH positive cells with cancer stem cell characterics, further investigation of IL-6/STAT3 as a potentially therapeutic target in NSCLC is warranted." (PMID 28830450, 2017). "Since pro-inflammatory cytokines play a critical role in the onset of cancer cachexia, we measured mRNA levels of IL6, TNFα, IL1β, and PTHrP32,33 in C26 tumors isolated from mice treated with vehicle, (−)-JQ1 and (+)-JQ1 (20 and 50 mg/kg/day)." (PMID 29167426, 2017). "Our observations also demonstrate that IL-6 and IL-8 work uniquely in a cell-autonomous manner through paracrine signalling amongst the same population of cancer cells." (PMID 28548090, 2017). "Pro-inflammatory cytokines such as interleukin-6 (IL6) and interferon-γ are secreted to recruit a Th1-induced immunoreaction with the recognition of cancer cells through the activation of macrophages, CD8+ T-cells, and natural killer cells." (PMID 29048388, 2017). "Of particular note, IL-6 is known as a direct promotor of cancer cell proliferation, induction of angiogenesis, and metastasis in inflammation-associated carcinogenesis and sporadic CRC." (PMID 28881611, 2017). "We observed a reduction in cancer stem cell migration when the IL-6 pathway was inhibited either with an IL-6 neutralizing antibody or with tocilizumab." (PMID 29245982, 2017). "The present review summarizes the most known cancer-related cytokines IL-2, IL-1, IL-4 and IL-6 as regulators of carcinogenesis and cancer maintenance or eradication." (PMID 28927416, 2017). "Dysregulated expression of CXCL1 and IL-6 have also been attributed to enhanced angiogenesis and tumorigenesis in cancer cells via constitutive activation of NF-κB." (PMID 28445977, 2017). "IL-6/Janus kinase 2 (Jak-2)/signal transducer and activator of transcription 3 (STAT3) pathway has been implicated as a key player in many cancer types." (PMID 28970500, 2017). "The study suggested a paracrine origin of IL-6 from the surrounding stroma cells, in addition to the autocrine production from the cancer cells themselves." (PMID 28927416, 2017).